UPK1B (uroplakin 1B)
Description:
Component of the asymmetric unit membrane (AUM); a highly specialized biomembrane elaborated by terminally differentiated urothelial cells. May play an important role in normal bladder epithelial physiology, possibly in regulating membrane permeability of superficial umbrella cells or in stabilizing the apical membrane through AUM/cytoskeletal interactions (By similarity).
Synonyms: UPIb; TSPAN20; UPK1
Tractability: Antibody: UniProt predicts a signal peptide or a membrane-spanning region.
Gene: Protein-coding gene on chromosome 3 (119,173,517 to 119,205,152, forward strand). Ensembl gene ENSG00000114638.
Subcellular location: Membrane
Gene Ontology:
Molecular function: protein binding; structural molecule activity
Biological process: epithelial cell differentiation
Cellular component: extracellular exosome; apical plasma membrane urothelial plaque; membrane; apical plasma membrane
Genetic constraint (gnomAD): Loss-of-function variants: 23 observed, 31.61 expected, observed/expected ratio (o/e) 0.73, 90% interval 0.52 to 1.03. The synonymous counts are far from expectation, so gnomAD's model fits this gene poorly and the ratio says little. Missense variants: 291 observed, 301.63 expected, observed/expected ratio (o/e) 0.96, 90% interval 0.88 to 1.06. Synonymous variants: 70 observed, 105.18 expected, observed/expected ratio (o/e) 0.67, 90% interval 0.55 to 0.81.
Homologues: Orthologues: chimpanzee UPK1B (99% identical), macaque UPK1B (99% identical), dog UPK1B (95% identical), pig UPK1B (94% identical), rabbit UPK1B (94% identical), guinea pig UPK1B (92% identical), mouse Upk1b (91% identical), rat Upk1b (89% identical), tropical clawed frog upk1b (68% identical). Paralogues in human: UPK1A (38% identical), TSPAN18 (23% identical), TSPAN4 (23% identical), CD151 (22% identical), TSPAN9 (22% identical), TSPAN17 (21% identical), CD63 (20% identical), TSPAN11 (20% identical), TSPAN6 (20% identical), TSPAN8 (20% identical), TSPAN1 (19% identical), TSPAN14 (19% identical), and 20 more.
Diseases named in the same sentence as UPK1B in open-access papers:
UPK1B is named in the same sentence as 24 diseases in open-access papers, as found by Europe PMC text mining. Sharing a sentence is not in itself a finding about the gene and the disease. The quoted sentences say what the papers report.
bladder cancer (16 papers, 2006 to 2025). "The marked decrease of both prevalence and intensity of Upk1a and Upk1b immunostaining from non-invasive (pTa) to muscle-invasive carcinomas (pT2-4) reflects a striking loss of Upk expression during bladder cancer progression." (PMID 37777995, 2024). "UPK1B, a member of the transmembrane four superfamily, was significantly associated with the prognosis and promoted the proliferation, migration and invasion by the Wnt/β-catenin signaling pathway in bladder cancer." (PMID 34566519, 2021). "UPK1B is a structural protein present in urothelial cells that is highly expressed in patients with bladder carcinoma." (PMID 37569864, 2023). "High expression of UPK1B in clinical samples of bladder cancer was highly correlated with lymph node metastasis, distant metastasis and advanced stage of tumor." (PMID 36367777, 2022). "The expression level of uroplakin-1b (UPK1B) is upregulated in bladder cancer, and it shows an oncogene function." (PMID 33564686, 2021). "Similarly, we found that uroplakin 1B (UPK1B) was overexpressed in bladder cancer, indicating its unique role in bladder tumor development." (PMID 33287876, 2020). "Finally, upk1b gene is highly expressed in normal human urothelium and its mRNA was undetectable or markedly reduced in bladder carcinoma." (PMID 16420690, 2006). "The XPERT© Bladder Cancer Monitor is a test for detecting the five mRNA sequences (ABL1, CRH, IGF2, UPK1B, ANXA10) in urine." (PMID 35804953, 2022). "Based on the detection of five mRNA targets in urine (CRH, IGF2, UPK1B, ANXA10, and ABL1), Xpert Bladder Cancer (Xpert BC) is a recently developed detector for the detection of bladder cancer, which is non-invasive and highly economical." (PMID 33563292, 2021). "Tspan20, also known as uroplakin 1B (UPK1B), promotes the invasion and metastasis of bladder cancer via regulation of the Wnt/β-catenin pathway, while the reduced expression of Tspan21 (UPK1A) might play a role in the progression of gastric cancer." (PMID 35046772, 2021). "UPK1B is irreversibly down-regulated by smoking and has been shown to be reduced or absent in bladder carcinomas through CpG methylation of the proximal promoter." (PMID 17894889, 2007).
colorectal cancer (2 papers, 2023 to 2025). A primary or metastatic malignant neoplasm that affects the colon or rectum. "UPK1B, which is a transmembrane tetraprotein, is associated with the tumorigenesis and progression of bladder, stomach, and colorectal cancers." (PMID 40114930, 2025). "UPK1B has been reported to be closely associated with tumor development, progression, and chemotherapy resistance in bladder, gastric and colorectal cancers." (PMID 38114532, 2023).
gastric cancer (2 papers, 2021). A primary or metastatic malignant neoplasm involving the stomach. "It is identified that UPK1B can be used as a biomarker to predict the chemotherapeutic outcomes of capecitabine and oxaliplatin in gastric cancer patients." (PMID 34222025, 2021).
urinary tract infection (2 papers, 2020 to 2022). "In addition, UPK1B is part of the innate immune system and has been associated with urinary tract infection by gram-negative bacteria in humans." (PMID 33193739, 2020). "Uroplakin 1a (TSPAN21) and Uroplakin 1b (TSPAN20) have been found to attach to the type 1 fimbriae, FimH adhesin of uropathogenic Escherichia coli that invaded the bladder epithelial cells leading to urinary tract infections in humans." (PMID 36101528, 2022).
breast carcinoma (1 paper, 2024). "It is also of note that Upk1a/Upk1b staining is only very rarely seen in breast cancer (0%–4%) and in salivary gland tumors (0%–10%)." (PMID 37777995, 2024).
diabetic nephropathy (1 paper, 2021). "Notably, three protein‐coding genes (Upk1b, Psca and Gdf15) and two lncRNAs (NONMMUG023520.2 and NONMMUG032975.2) were identified to be Smad3‐dependent and to be associated with the development of diabetic nephropathy." (PMID 33369170, 2021).
gastric tumor (1 paper, 2023). "The results obtained from reverse transcription-quantitative polymerase chain reaction (RT-qPCR) and immunohistochemical indicated that the expression levels of CGB5, UPK1B, and PI15 were downregulated in gastric tumor cells, while DNAAF3 was upregulated." (PMID 37711621, 2023).
lung carcinoma (1 paper, 2023). "But TSPAN11, UPK1B, and UPK1A are currently not related to lung cancer research." (PMID 37516981, 2023).
metastatic tumor (1 paper, 2024). "The TSPAN13, TSPAN31, and UPK1B genes were upregulated in the fibroblast compartment of metastatic tumor." (PMID 38255741, 2024). "Significant gene upregulation of these tetraspanins (CD53, ROM1, TSPAN3, TSPAN12, TSPAN15, and UPK1B) within immune cells in metastatic tumor suggests their potential involvement in the influence of immune responses." (PMID 38255741, 2024). "The upregulation of TSPAN13, TSPAN31, and UPK1B genes in the fibroblast compartment of metastatic tumor suggests their potential significance in the context of tumor–fibroblast interactions, metastasis, and the distinct characteristics of the metastatic microenvironment." (PMID 38255741, 2024).
urothelial carcinoma (1 paper, 2024). A malignant neoplasm derived from the transitional epithelium of the urinary tract (urinary bladder, ureter, urethra, or renal pelvis). "Uroplakin-1a (Upk1a) and uroplakin-1b (Upk1b) have recently been identified as diagnostic markers for the distinction of urothelial carcinomas from other solid tumor entities." (PMID 37777995, 2024). "The results of our study confirm a diagnostic utility of Upk1a and Upk1b IHC for the distinction of urothelial carcinomas from other tumor entities and also suggest a prognostic utility of Upk1a/Upk1b measurement as a part of a panel that distinguishes a “luminal” urothelial cancer phenotype." (PMID 37777995, 2024). "We thus studied the relationship between Upk1a and Upk1b immunostaining and clinicopathological parameters of disease progression as well as patient outcome in more than 2700 urothelial carcinomas in a tissue microarray (TMA) format." (PMID 37777995, 2024). "In summary, the results of our study demonstrate that Upk1a and/or Upk1b immunohistochemistry can complement GATA3 for the distinction of urothelial carcinomas." (PMID 37777995, 2024). "Both Upk1a and Upk1b were recently identified as useful IHC markers for the distinction of urothelial carcinomas from its morphological differential diagnoses in studies investigating 6929 and 14,061 tumors from more than 110 different cancer entities." (PMID 37777995, 2024). "In summary, the results of our study demonstrate that Upk1a and/or Upk1b IHC can well complement GATA3 for the distinction of urothelial carcinomas." (PMID 37777995, 2024). "In recent studies on more than 6500 tumors from more than 100 different cancer types, Upk1a and Upk1b have been identified as potential markers for the distinction of urothelial carcinomas from other tumor entities." (PMID 37777995, 2024). "Upk1a/Upk1b staining was observed in 32% of GATA3 negative pT2-4 cancers and GATA3 staining was seen in 43% of Upk1a/Upk1b negative pT2-4 urothelial carcinomas." (PMID 37777995, 2024).
tumor (12 papers, 2019 to 2025). "Parameters for luminal tumor phenotype—which was linked to favorable disease outcome in studies analyzing RNA—such as uroplakin 1a, uroplakin 1b, or GATA3 were also unrelated to patient outcome in our cohort of more than 600 muscle-invasive carcinomas in recent studies." (PMID 39680294, 2025). "From the RT-qPCR and immunohistochemical, the expression of DNAAF3 was higher in tumor and the expression of PI15, UPK1B, and CGB5 was lower in tumor." (PMID 37711621, 2023). "Results showed that some of the proteins found in EVs were shared among these cancer types, while others were tumour‐specific, and with respect to UC, the EVs expressed high levels of UPK1A, UPK1B, UPK2 and UPK3B." (PMID 35838333, 2022). "Additionally, the investigation of the expression of four signature genes in the tumor immune microenvironment through single-cell sequencing analysis confirmed the presence of CGB5, PI15, UPK1B, and DNAAF3 in the T cell cluster." (PMID 37711621, 2023). "While OSCC-LM showed no KRT13 and UPK1B expression, some tumor cells of LSCC showed KRT13 and UPK1B expression in 10 of 12 cases (83.3%)." (PMID 38114532, 2023).
cancer (6 papers, 2021 to 2024). A tumor composed of atypical neoplastic, often pleomorphic cells that invade other tissues. "Within pT2-4 carcinomas, high expression of Upk1a and Upk1b was linked to nodal metastasis and lymphatic vessel infiltration (p < 0.05) but unrelated to patient outcome." (PMID 37777995, 2024). "In addition, a comparison with GATA3 expression was conducted to further evaluate the diagnostic potential of Upk1a and Upk1b for identifying cancers of urothelial origin." (PMID 37777995, 2024). "Within the entire cohort of pT2-4 cancers, Upk1b staining was unrelated to pT status, histologic grade, and clinical disease course but high Upk1b expression was significantly associated with L1-status (p = 0.0002) and nodal metastasis (p < 0.0001)." (PMID 37777995, 2024). "Upk1b expression was unrelated to patient prognosis both in the analysis of all pT2-4 carcinomas and in subgroups of pT2, pT3 and pT4 cancers." (PMID 37777995, 2024). "GATA3 and Upk1a/Upk1b immunostaining showed a strong statistical correlation in our 1596 pT2-4 carcinomas with data on all three markers (p < 0.0001)." (PMID 37777995, 2024). "This adverse outcome may be due to UPK1B significantly influencing the expression of key genes in the Wnt/β-catenin signaling pathway in cancer cells." (PMID 39099656, 2024). "Furthermore, a progressive loss of Upk1a/b expression during stage progression and a prognostic role of the combination GATA3/Upk1a/Upk1b in pT4 carcinomas is evident." (PMID 37777995, 2024). "The downregulated genes that we have identified in NPC, such as MSMB, UPK1B, and FOXJ1, may be associated with the development or progression of NPC and may play different roles from their roles in other cancers." (PMID 33564686, 2021). "That the combination of Upk1a/Upk1b and GATA3 resulted in an even stronger association with patient survival and that this link was still completely limited to pT4 cancers may suggest that IHC panels identifying luminal type pT4 carcinomas may have clinical utility in the future." (PMID 37777995, 2024). "The fraction of Upk1a/Upk1b positive cases decreased slightly from pTaG2 low-grade (88% positive for Upk1a/87% positive for Upk1b) and pTaG2 high-grade (92%/89%) to pTaG3 (83%/88%; p > 0.05) and was lower in muscle-invasive (pT2-4) carcinomas (42%/64%; p < 0.0001/p < 0.0001 for pTa vs. pT2-4)." (PMID 37777995, 2024). "There were significant associations between Upk1a, Upk1b and GATA3 immunostaining (p < 0.0001 each), but 11% of GATA3 negative cancers were Upk1a/b positive and 8% of Upk1a/b negative cancers were GATA3 positive." (PMID 37777995, 2024). "Within pT2-4 carcinomas, only 11.2% of 706 Upk1a positive cancers were Upk1b negative while 41.2% of 1,076 Upk1b positive cancers were Upk1a negative (p < 0.0001)." (PMID 37777995, 2024). "The combined analysis of Upk1a and Upk1b revealed a link between high Upk1a/Upk1b expression and favorable patient prognosis in pT4 (p = 0.0365) but not in pT2 and pT3 carcinomas." (PMID 37777995, 2024). "However, GATA3 positivity was found in 31.5% of 476 Upk1a/Upk1b negative while Upk1a/Upk1b positivity was observed in 42.7% of 569 GATA3 negative pT2-4 cancers." (PMID 37777995, 2024).
UPK1B also shares sentences with these, for which no sentence is quoted: asthma (2 papers); infection (2); bladder tumor (1); invasive carcinoma (1); lung squamous cell carcinoma (1); lymph node metastasis (1); Obesity (1); oral squamous cell carcinoma (1); salivary gland tumors (1); Stroke (1); Ta (1); urothelial carcinoma of the bladder (1).